ALB (albumin)
Diseases named in the same sentence as ALB in open-access papers (continued):
Sharing a sentence is not in itself a finding about the gene and the disease.
tumor (continued). "An intriguing possibility is that endogenous proteases, by generating tryptic fragments of albumin, help to potentiate fibrocyte differentiation in wounds and tissues near a tumor edge." (PMID 23951012, 2013). "Other significant prognostic factors (p < 0.001) for mortality included APACHE II score, service, length of stay after the onset of infection, serum albumin, blood creatinine, neoplasms and hemodialysis." (PMID 22963041, 2012). "As shown by the IHC staining of albumin, the local induction of plasma albumin extravasation by NG29 was more localized at the invasion site (referred to as BAT) than at the tumor itself (approximatively 2- versus 1.5-fold increase, respectively)." (PMID 22629405, 2012). "Considering the microscopic size of ENU-induced hyperplasia at this age, it seems unlikely that the increased albumin reflects either albumin release from tumor cells or the impact of a space occupying lesion." (PMID 23185417, 2012). "It uses four criteria of ascites, albumin, bilirubin, and tumor size to assess liver functional status and tumor stage." (PMID 23197879, 2012). "Evans Blue-Albumin complexes were present primarily at the margin and around blood vessels in vital zones of the tumour." (PMID 22590529, 2012). "A fusion protein formed from human TIMP-2 and human serum albumin was found to provide an improved pharmacokinetic profile and biodistribution in a tumor model and to provide an antiangiogenic effect." (PMID 23185522, 2012). "Evans Blue-Albumin complex was present only around blood vessels, at the margin of the tumour, and in the transition zone between vital tumour tissue and central necrosis and thus was similar to the T84.1 binding." (PMID 22162753, 2011). "In experimental animals bearing solid tumours radioactively-or fluorescently labelled albumin was taken up into tumours specifically." (PMID 21676260, 2011). "Under conditions of cellular stress, as in growing tumour tissue, albumin is taken up by cells as a source of amino acids and energy." (PMID 21676260, 2011). "Tumors spots for hemoglobin, apolipoprotein A1, serum albumin, and alpha-2 globulin were five times larger than the same spots from non-tumorous extracts." (PMID 21470419, 2011). "The sum of spectra for these housekeeping proteins was normalized by the number of albumin spectra identified in tumor fluid and frozen tumor fluid, respectively." (PMID 21541282, 2011). "Human serum albumin (HSA) represents a biodegradable drug carrier system with the capacity of delivering a large payload of cytotoxic drug to the tumor site." (PMID 21845098, 2011). "In this study, male, AST > 34IU/L, albumin ≦ 3.5 g/dl, AFP > 15 ng/ml, tumor size >5 cm in diameter were the risk factors of tumor recurrence." (PMID 21269525, 2011). "A study investigating the relationship between the serum levels of high sensitivity CRP (H-CRP) and the prognosis of HCC patients found positive H-CRP, albumin, tumor stage and initial treatment to be significant independent determinants of poor prognosis." (PMID 21176210, 2010). "Univariate analysis indicated that the serum albumin level, Child classification, number of tumor foci, portal venous invasion-targeted irradiation, and percutaneous tumor ablation of the parenchymal main tumor were significant." (PMID 21176210, 2010). "A study conducted in 403 patients with HCC found serum albumin, bilirubin, size of the tumor, and number of tumor nodules to be independent predictors of survival." (PMID 21176210, 2010). "SPARC (secreted protein acidic and rich in cysteine), a protein overexpressed and secreted by cancer cells, binds albumin to concentrate albumin-bound cytotoxic drugs at the tumor." (PMID 21144040, 2010).
tumor (continued). "Both hemoglobin and albumin were identified as significantly (p ≤ 0.05) up-regulated in the fresh frozen lysates of normal samples compared with the tumor samples." (PMID 20187940, 2010). "Factors related to repeat hepatectomy included the following: female gender, younger age, tumor grade, microscopic vascular invasion, recurrent tumors >3 cm, and serum albumin level <35 g/L." (PMID 20591196, 2010). "The effect of PDGF and VEGF receptor inhibitors on tumor vessel leakiness was determined by injection of Evans blue, a dye that quantitatively binds to albumin in the circulation." (PMID 19997591, 2009). "Using univariate analysis of cancer-specific survival, we found that sex (P = 0.002), tumor size (P = 0.015), serum albumin level (P < 0.001), histology (P < 0.001), UICC stage (P < 0.001) and serum CEA level (P < 0.001) were statistically significant." (PMID 19691850, 2009). "The appearance of AFP and ALB in the medium further confirms tumor cell de-differentiation and differentiation, respectively." (PMID 19604375, 2009). "Then, 0.8 mCi (30 MBq) to 1.4 mCi (50 MBq) of 99mTc human nanocolloidal albumin within 0.3 ml of normal saline solution was injected superficially into the subepithelial stroma in four points around the tumor." (PMID 19173715, 2009). "Those with focal tumor, tumor volume <70%, aminotransaminases level <5 of upper limit, biluribin level <2 mg/dl, and albumin <3 g/dl, had higher 3 months mortality (49% vs. 7%)." (PMID 19568509, 2008). "On multivariate analysis, only tumour size (P<0.05), albumin (P<0.01) and systemic treatment (P<0.0001) were significant independent predictors of relapse-free, cancer-specific and overall survival." (PMID 17375036, 2007). "Tumour vessel permeability was measured by i.p. injection of Evans blue dye, a dye with a strong affinity for serum albumin." (PMID 15812555, 2005). "The aim of the present study was to examine the relationship between circulating albumin concentration, the tumour burden and the systemic inflammatory response in patients with colorectal liver metastases." (PMID 15213726, 2004). "When multivariate analysis was performed, however, only age, low postprocedural albumin (<35 g l−1) and tumour response to CT scan remained significant." (PMID 14562011, 2003). "On univariate survival analysis, stage (P<0.05), tumour type (P<0.01), performance status (P<0.001), white cell count (P<0.01), albumin (P<0.001) and C-reactive protein (P<0.01) were significant predictors of survival." (PMID 12966420, 2003). "Vascular permeability was measured by diffusion of radiolabelled 131I albumin in liver and tumour tissue." (PMID 12610519, 2003). "With respect to HCC, both albumin and α-FP mRNA are widely used as tumour markers for HCC cells in circulation." (PMID 11857021, 2002). "At constant flow, the pressure gradient generated in the tumour by the infusion of fluid (Evans blue-albumin in saline) was measured as a function of the radial position with micropipettes connected to a servo-null system." (PMID 9836476, 1998). "The level of tumour lipids was also higher in the MAC16 than in the MAC13 tumour after both an oral [14C]lipid load or by direct injection of [U-14C]palmitate complexed to albumin into epididymal fat pads." (PMID 1637677, 1992). "Regional albumin microspheres were delivered to tumour in greater proportions (mean T/N ratio 3.89, SE 0.49) than would be expected from baseline hepatic arterial blood flow (mean T/N ratio 1.28, SE 0.22." (PMID 1503900, 1992). "Cryopreserved tumour cell preparations were used to allow repeated testing of the same target, and the tumour cells were fractionated using albumin density gradients to determine if fractions containing clonogenic (stem) cells were killed." (PMID 3264715, 1988).
tumor (continued). "The effects of X-radiation on the Nembutal-induced redistribution of the cardiac output in two types of transplanted mouse tumours and some normal mouse tissues have been investigated, using rubidium-86 and 125I-human serum albumin." (PMID 1067860, 1976). "Relative increases were seen in the extravascular distribution of albumin, due partly to albumin pooling in and around the tumours and possibly also to general increases in capillary permeability." (PMID 5115834, 1971). "Albumin concentrations were reduced in the tumour bearing animals but plasma volumes increased as the tumours developed." (PMID 5115834, 1971). "Combining EGFR-targeted delivery with albumin-based nanocarriers thus offers a powerful dual strategy: the targeting ligand directs the carrier to EGFR-overexpressing tumor sites, while albumin ensures stability, biodegradability, and efficient intracellular transport." (PMID 41489768, 2026). "In addition, age, BMI, NRS-2002 score, CEA level, pathological T stage, pathological N stage, tumor differentiation, vascular invasion, adjuvant therapy, white blood cell count, albumin and hemoglobin levels were significant predictors of DFS." (PMID 41602396, 2026). "Importantly, in the current study, collinearity between tumor extension, albumin levels and resection status must be considered when interpreting results from the multivariable regression." (PMID 41504962, 2026). "In addition to nab-paclitaxel, many albumin-based formulations and nanoparticles are under development, leveraging the safety, biocompatibility, and inherent tumor-homing capabilities of albumin to create more effective and targeted cancer therapies." (PMID 41489768, 2026). "This discrepancy may be attributed to variation in tumor types and the unit of serum albumin measurement utilized in different studies." (PMID 41601773, 2026). "Importantly, Albumin@MnB enhances intratumoral immune cell infiltration and suppresses distant tumor growth, synergizing with adoptive T cell immunotherapy and immune checkpoint inhibitors." (PMID 41743161, 2026). "The design of multistimuli-responsive albumin nanocarriers that react to specific tumor microenvironment cues could enhance drug release control and therapeutic outcomes." (PMID 41489768, 2026). "Recent studies have demonstrated that lipid-conjugated siRNAs engineered for optimal in situ binding to serum albumin exhibit dramatically enhanced pharmacokinetics and tumor accumulation, with up to 12-fold increased delivery to orthotopic TNBC tumors compared with unconjugated siRNAs." (PMID 41489768, 2026). "In parallel, recent advances have expanded the versatility of albumin nanoplatforms, ranging from transformable nanocapsules that modulate tumor metabolism to albumin-hitchhiking immune conjugates that enhance tumor accumulation and potentiate antitumor responses 14,15." (PMID 41355949, 2026). "Univariate Cox regression analysis revealed that age, NRS-2002 score, CEA, CA19-9, pathological T stage, pathological N stage, tumor differentiation, vascular invasion, adjuvant therapy, white blood cell count, albumin and hemoglobin were significant predictors of OS." (PMID 41602396, 2026). "We hypothesized that the lactate dehydrogenase-to-albumin ratio (LAR), as an integrative tumor-host biomarker, may provide biologically informed risk stratification in this setting." (PMID 42195199, 2026). "Covalent conjugation chemically attaches drugs to albumin with the help of cleavable linkers that respond to tumor-specific stimuli such as low pH, hypoxia, or tumor-overexpressing enzymes, which allows targeted drug release in the tumor microenvironment with reduced systemic toxicity." (PMID 41489768, 2026). "Nab-paclitaxel exploits albumin’s solubilizing capacity and tumor-targeting mechanisms to enhance the delivery of paclitaxel, achieving higher tumor drug concentrations and improved therapeutic responses while reducing the solvent-related toxicity common to conventional formulations." (PMID 41489768, 2026).
tumor (continued). "Tumor burden induces chronic inflammation and consumes albumin, leading to decreased AAPR." (PMID 41601745, 2026). "Cumulatively, these challenges are multifaced and highlight the need for a concerted strategy that integrates rational design, tumor biology knowledge, and sophisticated manufacturing to comprehensively unlock the therapeutic potential of albumin-based nanomedicines in TNBC." (PMID 41489768, 2026). "Alcohol metabolites will inevitably induce accumulation of gene mutations in liver cells, once ALB+KRT7+ population transform to malignant cells due to gene mutation or other malignant cells appear, the existing ALB+KRT7+ populations promote the tumour initiation and progression." (PMID 39834100, 2025). "Albumin-absorbing and the intrinsic -S-S-S-S- bond in the framework of deformable HSMONs made it long-circulating in the blood and led to lung tropism; after arriving at lung tissue, HSMONs were largely endocytosed to tumor cells due to their deformability." (PMID 41304726, 2025). "Furthermore, albumin plays a vital role as a transporter for tumor drug delivery, attributed to several factors." (PMID 41142425, 2025). "The cell viability and IC50 values of the cell lines decreased with increasing time after treatment with HSA NP-mediated tumor-targeted Dox/OA combination therapy Human Serum Albumin Nanoparticle-mediated tumor-targeted Doxorubicin/ OA combination therapy (Dox@HSA-OA)." (PMID 39926108, 2025). "Additionally, albumin's natural affinity for tumor microenvironments has inspired investigations into its use for simultaneous antimicrobial and anticancer therapies." (PMID 40343307, 2025). "Multiple regression analysis showed the size of the largest tumor nodule, the number of nodules, macrovascular invasion, extrahepatic metastasis, total bilirubin, albumin, prothrombin time (PT), α-fetoprotein, and des-γ-carboxyprothrombin (DCP) as independent predictors of survival." (PMID 41090669, 2025). "Although albumin binders are generally designed to delay blood clearance, thereby increasing tumor accumulation and reducing renal uptake, some recent reports have emphasized that the actual pharmacokinetic profile depends heavily on binder affinity, molecular linkage, and isotope half-life." (PMID 40724817, 2025). "Moreover, the albumin nanoparticles leverage the enhanced permeability and retention (EPR) effect—a hallmark of tumor vasculature—to selectively accumulate in tumor tissues." (PMID 40343307, 2025). "The increased tumor uptake and retention of [89Zr]­Zr-DFO*malHSAat late time points has not been reported yet and is consistent withthe suggested molecular mechanisms underlying tumoral albumin homeostasis,likely enabled by the EPR effect." (PMID 40526060, 2025). "The elevated levels of neutrophils and higher tumor burden during tumor progression lead to a decrease in the body's own albumin levels, which may explain why increased NPAR levels are associated with a higher risk of mortality." (PMID 39831739, 2025). "Notably, we observed increased infiltration levels of Tregs, a pivotal immunosuppressive CD4+T cell that promote tumour progression, in high‐ALB+KRT7+ EPCs group." (PMID 39834100, 2025). "Albumin-bound paclitaxel has been approved for the treatment of breast cancer, non-small cell lung cancer, and pancreatic cancer, demonstrating good anti-tumor activity." (PMID 41550955, 2025). "Additionally, albumin nanoparticles can be surface-functionalized with targeting ligands such as antibodies, peptides, and folic acid to improve tumor specificity and receptor-mediated uptake." (PMID 40699702, 2025). "In addition, passive tumor targeting can also be achieved through protein-dye complexes formed with albumin or components of fetal bovine serum (FBS) via hydrophobic interactions or covalent bonds." (PMID 41305285, 2025).
tumor (continued). "For both newly diagnosed (n = 74) and recurrent patients (n = 97), univariate and multivariate regression analyses were conducted to assess the impact of sex, age, KPS, albumin levels, cholesterol levels, benzodiazepine use, smoking history, and tumor location on survival." (PMID 40284018, 2025). "Furthermore, 97% of HCCs showed albumin positivity in >50% of tumor cells, compared to only 76% for HepPar1 and 70% for Arg-1." (PMID 40941632, 2025). "Moreover, we have demonstrated that these CRT agents exhibit dual binding to albumin and DNA, enabling non-invasive tumor visualization by PET imaging while concurrently delivering therapeutic effects." (PMID 40867175, 2025). "Notably, functional abilities, such as transfer, and clinical factors, such as albumin and neoplasms, consistently contributed to fall prediction across the models." (PMID 41343780, 2025). "Importantly, 99mTc-labeled human serum albumin scintigraphy demonstrated focal protein leakage at the tumor site, providing strong evidence that malignancy was the direct cause of PLE." (PMID 41497708, 2025). "These structural modificationsshould prevent SST2 binding and residual tumor uptake (ifat all) might then originate from the albumin-bound radioligand and/oroff-target binding by the albumin-binding moiety itself." (PMID 40393943, 2025). "Tumor cells also take in albumin as a nutrient through micropinocytosis." (PMID 40296757, 2025). "Albumin also exerts antioxidant and anti-inflammatory effects, and its depletion contributes to oxidative stress and a prothrombotic state that may favor tumor progression and metastasis." (PMID 41347085, 2025). "Additionally, the collapse of lymphatic drainage ensures that albumin remains within the tumor tissues." (PMID 41142425, 2025). "Albumin, the most abundant protein in blood plasma, serves as a natural transport vehicle, and nanoparticles derived from it can exploit endogenous uptake pathways (e.g., via the gp60 receptor) that are often upregulated in tumor cells." (PMID 41154612, 2025). "Moreover, decreased ALB lowers plasma colloid osmotic pressure, leading to tissue edema and a hypoxic tumor microenvironment." (PMID 41256327, 2025). "Nevertheless, increased child-pugh grade, tumor status, surrounding hepatic tissue inflammation, and albumin were not linked to increased expression of ACTR6." (PMID 40130245, 2025). "In addition, some experimental studies have shown that albumin exerts protective effects by regulating tumor growth factors in HCC." (PMID 40181742, 2025). "The advent of nanotechnology in oncology drug delivery catalyzed the development of nanoparticle albumin-bound paclitaxel (nab-paclitaxel), a formulation designed to circumvent these limitations by leveraging endogenous albumin pathways for enhanced tumor-specific accumulation." (PMID 41415558, 2025). "Secondly, albumin demonstrates high tumor accumulation due to the EPR effect." (PMID 41142425, 2025). "In the multivariate Cox regression analysis including ferritin, T-stage, G-stage, tumor size, N-stage, albumin, and CA19-9, elevated preoperative serum ferritin remained a significant independent prognostic factor for overall survival (HR = 2.85; 95% CI: 1.41–5.76; p = 0.004)." (PMID 40397178, 2025). "The albumin-bound and liposomal encapsulation technologies have facilitated higher drug concentrations at tumor sites, improved penetration into tumor tissues, and provided options for patients who are refractory or have developed resistance to standard therapies." (PMID 40697515, 2025). "Therefore, LAR, which combines LDH and ALB, can comprehensively reflect the tumor burden and the overall metabolic and inflammatory status of patients." (PMID 41377338, 2025). "Albumin has demonstrated certain distinct benefits, particularly for tumor treatment." (PMID 40699702, 2025).